UBQLN1 (ubiquilin 1)
Diseases named in the same sentence as UBQLN1 in open-access papers (continued):
Sharing a sentence is not in itself a finding about the gene and the disease.
tumor (13 papers, 2013 to 2026). "One study published in 2022 proved that loss of UBQLN1 induces tumor progression and metastasis, including proliferation, clonogenic potential and migration in A549 cell lines." (PMID 38431566, 2024). "We found that peritumoral siRNA‐mediated UBQLN1 knockdown significantly attenuated tumor growth, with western blot confirmation of successful UBQLN1 reduction and concomitant GPX4 downregulation." (PMID 41287824, 2025). "Immunohistochemistry was performed to detect UBQLN1 expression in 88 LC tissues and 88 para-tumor tissues." (PMID 38431566, 2024). "Following subcutaneous inoculations of generated cell lines, we observed an increase in tumor volume and lung metastasis in mice injected with A549 cells expressing UBQLN1 shRNA compared to mice injected with A549 cells expressing control shRNA." (PMID 37444499, 2023). "Three tumor-associated candidates (RBM4, GOLGA4 and UBQLN1) were selected to validate the RNA-seq data." (PMID 37415951, 2023). "Immunohistochemistry was performed to evaluate UBQLN1 levels in tumor tissues, and patients were divided into two groups according to UBQLN1 levels." (PMID 34001851, 2021). "Taken together, these clinical and in vivo data further demonstrate the role of UBQLN1 in promoting HCC tumor progression and sorafenib resistance." (PMID 34001851, 2021). "Only tumor diameter was significantly correlated with UBQLN1 expression (P<0.05)." (PMID 38431566, 2024). "Additionally, Tumor growth curves indicated that reduced UBQLN1 inhibited tumor growth in terms of volumes." (PMID 37370699, 2023). "Furthermore, the AUC of UBQLN1 protein is 0.867 in differentiating ADC from para-tumor tissues." (PMID 38431566, 2024). "In parallel, upon RUNX2 knockdown, we have observed a predominant and strong downregulation of gene nodes known to be implicated in EOC tumorigenesis (PTGS1/COX1, FGF2, IL1A, Sapk, C/ebp, SELE, UBQLN1, PSAT1, ALDH1A1, GDF15, MTHFD2), including EOC tumor invasion/metastasis (MMP1, MMP13, Creb);." (PMID 24124450, 2013). "Moreover, UBQLN1-3 showed upregulation when comparing tumors to normal respective specimens obtained from GTEx, but not when compared to tumor adjacent normal tissue using TCGA datasets." (PMID 36291176, 2022).
neurodegenerative disease (7 papers, 2014 to 2025). A disorder of the central nervous system characterized by gradual and progressive loss of neural tissue and neurologic function. "Most studies on UBQLN1 have focused on its function in neurodegenerative diseases." (PMID 34515612, 2021).
infection (3 papers, 2011 to 2015). The state of being infected such as from the introduction of a foreign agent such as serum, vaccine, antigenic substance or organism. "Here, we provide multiple lines of evidence that UBQLN1 associates with Mtb and links them to the autophagy machinery: UBQLN1 binds MUPs, binds Mtb in vitro, and localizes to Mtb during infection." (PMID 26225865, 2015). "To determine whether UBQLN1 plays a role during infection, we examined macrophages in which UBQLN1 was depleted using RNAi." (PMID 26225865, 2015).
lung (1 paper, 2024). "In Section 2: (a) the expression of UBQLN1 protein was detected in 88 lung ADC tissues and 88 adjacent normal tissues." (PMID 38431566, 2024).
UBQLN1 also shares sentences with these, for which no sentence is quoted: hepatocellular carcinoma (5 papers); non-small cell lung carcinoma (3); frontotemporal dementia (2); lymph node metastasis (2); motor neuron disease (2); neurological disorders (2); Stroke (2); adenocarcinoma (1); astrocytoma (1); autism (1); cognitive decline (1); dementia (1); diffuse Lewy body disease (1); heart diseases (1); injury (1); leprosy (1); melanoma (1); myocardial ischemia (1); Onset (1); Parkinson’s (1); schizophrenia (1); squamous cell carcinoma (1); squamous cell carcinoma of lung (1); tuberculosis (1).